JAK2 (Janus kinase 2)
Diseases named in the same sentence as JAK2 in open-access papers (continued):
Sharing a sentence is not in itself a finding about the gene and the disease.
gastric cancer (continued). "It certainly will be very interesting to further explore the potential effectiveness of those molecules targeting miR-375, JAK2 or Snail in the treatment of gastric cancer." (PMID 25055044, 2014). "Given the critical role of miR-375 and JAK2 as master regulators in gastric cancer cells proliferation, migration, and invasion, both of them has therapeutic potential in gastric cancer treatment." (PMID 25055044, 2014). "Excitingly, our study first demonstrated that knocking down JAK2 by RNAi inhibited the migration and invasion activities of gastric cancer cells similar to that of the overexpression of miR-375." (PMID 25055044, 2014). "Our previous study showed that miR-375 frequently downregulated in gastric cancer suppresses cell proliferation by targeting Janus kinase 2 (JAK2)." (PMID 25055044, 2014). "We found that overexpression of miR-375 inhibited proliferation, migration, and invasion of gastric cancer cells partially by targeting JAK2." (PMID 25055044, 2014). "Ectopic expression of miR-375 inhibits the migration and invasion of gastric cancer cells partially by targeting JAK2." (PMID 25055044, 2014). "Another interesting topic for future research will be the identification of other possible targets of miR-375, and, more specifically, the possible involvement of JAK2 in gastric cancer metastasis." (PMID 25055044, 2014). "In our previous study, miR-375 was significantly downregulated in gastric cancer and inhibited gastric cancer cells proliferation by targeting JAK2." (PMID 25055044, 2014). "Together this data supports efforts to further develop and apply inhibitors of JAK2/STAT3 pathway as therapeutic agents for gastric cancer treatment." (PMID 24804649, 2014). "Our studies uncovered that ectopic expression of miR-375 inhibited the migration and invasion of gastric cancer cells also partially by targeting JAK2." (PMID 25055044, 2014). "Together, our results provide an undescribed pathway, in which a transcription factor Snail regulates the expression of miR-375, which suppresses its direct target JAK2, leading to inhibit the migration and invasion of gastric cancer cells." (PMID 25055044, 2014). "Based on these previous observations, this hospital-based case-control study was conducted to assess the role of JAK2 SNPs in gastric cancer." (PMID 23717640, 2013). "miR-375 is frequently down-regulated in gastric cancer and function as a tumor suppressor to regulate gastric cancer cell proliferation potentially by targeting the JAK2 oncogene." (PMID 23554909, 2013). "TANs produce IL-17a, which promotes EMT of GC cells through JAK2/STAT3 signaling in gastric cancer." (PMID 40564191, 2025). "TANs activate the JAK2/STAT3 pathway in gastric cancer cells by secreting interleukin-17a (IL-17a)." (PMID 39050856, 2024). "Notably, these TANs produced IL-17A, enhancing the migration, invasion, and epithelial–mesenchymal transition (EMT) of gastric cancer cells through the activation of the Janus kinase 2/signal transducers and activators of transcription (JAK2/STAT3) pathway." (PMID 38474175, 2024). "It is commonly acknowledged that JAK2/STAT3 has a role in the development of gastric cancer." (PMID 38305998, 2024). "Furthermore, PA inhibited the nuclear localization of p-STAT3, indicating its potential to inhibit the proliferation and metastasis of gastric cancer cells by suppressing the JAK2/STAT3 immune signaling pathway." (PMID 37637038, 2023). "Among them, INF-γ, IL-17 and IL-21, and B-cell inflammatory genes are significantly increased in people with CAD, and IL-17a promotes the epithelial to mesenchymal transition in gastric cancer cells through JAK2/STAT3, exacerbating the development of gastric cancer." (PMID 36970364, 2023). "In addition, Calmodulin2 (CALM2) has been found to exhibit high expression in gastric cancer (GC) cells, modulating the JAK2/STAT3/HIF-1/VEGFA axis, promoting macrophage polarization, and facilitating ECs angiogenesis." (PMID 37666809, 2023).
gastric cancer (continued). "Wang and colleagues indicated that the MGP protein could directly bind to the p-STAT5 in the nucleus and activate JAK2/STAT5 signaling in gastric cancer, further facilitating tumor progression." (PMID 36276992, 2022). "Relevant to both OSCC and EBV+-gastric cancer, JAK2/STAT1 signaling has been shown to mediate respectively EGFR- or IRF-1, IFNγ-induced upregulation of the programmed cell death-ligand 1 (PD-L1), an inhibitor of T-cell-mediated tumor cytotoxicity as discussed later in this review." (PMID 35844493, 2022). "Pearson’s correlation analysis using data from 37 gastric cancer cell lines showed that ERCC6 mRNA expression was significantly correlated with JAK2 protein expression (r = −0.345; P = 0.037), and ERCC8 mRNA expression was associated with Src protein expression (r = −0.417; P = 0.010)." (PMID 34316408, 2021). "For example, SIRT6 inhibits the JAK2/STAT3 pathway to suppress the growth of gastric cancer." (PMID 33510943, 2021). "In addition, miR-375-3p has been shown to be implicated in gastric cancer through interaction with the components of the JAK-STAT pathway, while JAK2 blockade led to tumor growth inhibition and apoptosis in GIST." (PMID 32708220, 2020). "Moreover, TANs were localized mainly at the invasive margin of human gastric cancer tissues and expressed abundantly IL-17, which enhanced the migration, invasion and EMT of gastric cancer cells, through the activation of JAK2/STAT3 pathways." (PMID 32422991, 2020). "As the IL-6-induced transcriptional stimulation of MMP-9/2 results from the activation of STAT3 via the JAK2/STAT3 pathway in gastric cancer and AGS cells, we tested the STAT3 phosphorylation level in MKN-28 and AGS cells exposed to rIL-6 for different time points." (PMID 31817563, 2019). "Furthermore, inhibition of JAK2/STAT3 pathway suppresses the growth of gastric cancer in vitro and in vivo." (PMID 31540495, 2019). "JAK2 is an important tumor oncogene for several cancers including gastric cancer and lung cancer." (PMID 30361290, 2018). "In summary, SHP-1 as an effective phosphatase for inactivation of JAK2/STAT3 might be applied in gastric cancer and pantoprazole showed significant modulating effect on SHP-1/JAK2/STAT3 signaling axis in stomach cancer." (PMID 30202514, 2018). "Moreover, knockdown the expression of IL-6 in CAFs by RNAi or inhibiting JAK2/STAT3 pathway in gastric cancer cells by the specific inhibitor AG490 significantly retards the tumor peritoneal metastasis induced by CAFs in vivo." (PMID 28186964, 2017). "Moreover, silencing IL-6 expression in CAFs or inhibiting JAK2/STAT3 pathway in gastric cancer cells impairs tumor peritoneal metastasis induced by CAFs in vivo." (PMID 28186964, 2017). "We further examined whether block the JAK2/STAT3 pathway by AG490 could also inhibit the tumor-promoting effects on gastric cancer cells via the secretion of IL-6 by CAFs." (PMID 28186964, 2017). "Interestingly, ERK1/2 inhibition has been reported to enhance apoptosis induced by JAK2 silencing in human gastric cancer SGC7901 cells." (PMID 25742792, 2015). "Indeed, in gastric cancer, miR-375 forced expression increased apoptosis and reduced of cell viability in vitro, and janus kinase 2 (JAK2) was identified as a direct target." (PMID 25977730, 2015). "Here, we are interested in studying whether JAK2 is involved in the regulation of gastric cancer cells migration and invasion." (PMID 25055044, 2014). "Our data indicates that restoration of miR-375 or inhibition of Snail or JAK2 may be useful therapeutic strategies for gastric cancer treatment." (PMID 25055044, 2014). "Thus, our findings demonstrate that miR-375 inhibits gastric cancer cells migration and invasion through Snail/miR-375/JAK2 regulation pathway." (PMID 25055044, 2014). "Taken together, these data suggest that miR-375 may be negatively regulated by Snail and involved in gastric cancer cell migration and invasion potentially by targeting JAK2." (PMID 25055044, 2014).
gastric cancer (continued). "In the subgroup analyses, we found that JAK2 polymorphisms were associated with increased the risk of gastric cancer in males and nonsmokers." (PMID 23717640, 2013). "Nevertheless, to our knowledge, there is still no report on the association between JAK2 polymorphisms and the risk of gastric cancer." (PMID 23717640, 2013). "Inhibition of JAK/STAT pathway by demethylation treatment or by applying specific JAK2 inhibitor may open up a new therapeutic strategy against gastric cancer." (PMID 15354212, 2004). "Similarly, cancer-associated fibroblasts (CAF) in the tumor microenvironment promote the progression of gastric cancer through IL-6/JAK2/STAT3 signaling and achieve a targeted therapeutic effect on gastric cancer through the action of IL-6 on stromal fibroblasts." (PMID 35528617, 2022). "A recent study on GC has shown that C3 deposited in the tumor microenvironment can independently activate the JAK2/STAT3 pathway, and promote tumor progression, indicating its potential as a prognostic factor for patients with gastric cancer." (PMID 33193896, 2020). "Therefore, concurrent eradication of H. pylori and inhibition of JAK-STAT signaling cascade by applying specific JAK2 inhibitors may unravel new therapeutic strategies against the gastric cancer in ethnic Kashmiri population." (PMID 33569347, 2020). "Taken together, these results suggest that CAFs in the tumor microenvironment promote the progression of gastric cancer through IL-6/JAK2/STAT3 signaling, and IL-6 targeted therapy could be a complementary approach against gastric cancer by exerting their action on stromal fibroblasts." (PMID 28186964, 2017). "Thus, in consistent with our hypothesis, miR-375 may inhibit the migration and invasion of gastric cancer cells partially by targeting JAK2." (PMID 25055044, 2014). "Furthermore, it was reported that JAK2 was an oncogene and down-regulating the expression of JAK2 could significantly suppress the proliferation of gastric cancer cells." (PMID 23717640, 2013). "Therefore, JAK2 might be crucial for the coordinated proliferation, differentiation and tumorigenesis of gastric cancer." (PMID 23717640, 2013). "In gastric cancer tissues, neutrophils produce IL-17A, and TANs-derived IL-17A promotes the migration, invasiveness, and EMT of gastric cancer cells by activating the JAK2/STAT3 pathway." (PMID 40387965, 2025). "Inhibition of this pathway, using IL-17A neutralizing antibodies or the JAK2-specific inhibitor AG490, reverses these TAN-induced phenotypes in gastric cancer cells." (PMID 40387965, 2025). "Overexpression of RBMS1 in HGC-27 and SGC-7901 cells increased the migration and invasion of gastric cancer cells by binding to the transcription factor MYC and activating the IL-6/JAK2/STAT3 signaling pathway." (PMID 41214391, 2025). "TANs secrete IL-17A via the JAK2/STAT3 signaling pathway, which promotes EMT in gastric cancer cells." (PMID 40387965, 2025). "In gastric cancer cells, single stranded interacting protein 1 (RBMS1) was discovered to activate the JAK2/STAT3 downstream signaling pathway after binding to the transcription factor MYC, subsequently increasing cancer migration and invasion." (PMID 38182570, 2024). "In gastric cancer, IL6 can exert its influence on invasion and progression via the activation of the JAK2/STAT3 pathway, which is the well-known signaling pathway induced by IL6." (PMID 39251966, 2024). "Activating JAK2/STAT3 signaling pathway promotes EMT, migration, and invasion of gastric cancer cells, and promotes the transformation of quiescent gastric CSCs into invasive gastric CSCs." (PMID 39906741, 2024).
gastric cancer (continued). "Lijuan Ma reported that the JAK2/STAT3 signaling axis plays a key role in mediating endoplasmic reticulum stress, thus influencing the response of gastric cancer cells to 5-FU therapy and their autophagic processes, with ATF6 at the operational core." (PMID 39309860, 2024). "Using mouse models, they showed that high miR-375 levels can decrease the activity of the JAK2/STAT3 pathway, leading to the downregulation of PD-L1 in gastric cancer." (PMID 39309860, 2024). "Apigetrin also inhibits gastric cancer progression by inducing apoptosis and regulating the ROS-modulated STAT3/JAK2 pathway." (PMID 39795089, 2024). "The expression pattern of p-JAK2, which functions upstream of p-STAT3, were lower in the 150μM PA-treated human gastric cancer cell lines (MGC-803, AGS, and SGC-7901) than in the BSA-treated cell lines." (PMID 36672337, 2023). "In conclusion, we identified vortioxetine hydrobromide, a novel dual JAK2/SRC inhibitor, inhibited gastric cancer cell proliferation, through reducing STAT3 dimerization and nuclear translocation in vivo and in vitro." (PMID 37147297, 2023). "As p-STAT3 is a molecular marker of proliferation, our findings suggest that PA blocks the proliferation of human gastric cancer cells by inhibiting p-STAT3 and p-JAK2 expression." (PMID 36672337, 2023). "Some studies have demonstrated that the Janus-activated kinase 2 (JAK2)/signal transducer and activator of transcription 3 (STAT3) pathway are correlated with tumor progression, such as gastric cancer, colorectal cancer, and hepatocellular carcinoma." (PMID 36814203, 2023). "In this study, we found that vortioxetine hydrobromide is a dual JAK2/SRC inhibitor and suppresses the growth of gastric cancer cells in vivo and in vitro." (PMID 37147297, 2023). "We demonstrated that PA treatment for 12 h decreased the expressions of p-STAT3, p-JAK2, N-cadherin, and vimentin, and inhibited the nuclear expression of p-STAT3 in gastric cancer cells." (PMID 36672337, 2023). "SNHG16 sponged miR-135a and promoted Janus-activated kinase 2 (JAK2) and transcription Factor 3 (STAT3) expression in gastric cancer." (PMID 36949429, 2023). "For instance, asiatic acid derivatives have been found to suppress JAK2 and STAT3 activation, inhibiting gastric cancer cell proliferation and invasion." (PMID 37375849, 2023). "In this study, we find that vortioxetine hydrobromide, an FDA-approved drug, is a dual JAK2/SRC inhibitor, and has inhibitory effects on cell proliferation of gastric cancer." (PMID 37147297, 2023). "For example, miR-106a-3p induced apatinib resistance in gastric cancer cells by targeting the Cytokine signaling (SOCS) system and activating Jak2/Stat3 signaling." (PMID 35600882, 2022). "This study demonstrated that JAK2/STAT3 signaling pathway regulated various cytokines and growth factors that play an important role in gastric cancer cell growth." (PMID 35207737, 2022). "Apigetrin inhibits gastric cancer progression by inducing apoptosis and regulating the ROS-modulated STAT3/JAK2 pathway." (PMID 36445338, 2022). "Another study, which applied different doses and treatment durations of TQ to human gastric cancer cells, found that TQ reduced phosphorylation of STAT3 and its upstream kinases, including c-Src and Janus kinase-2 (JAK2)." (PMID 35236304, 2022). "Gastric cancer derived mesenchymal cells secrete IL-6 and IL-8 (CXCL8) through JAK2/STAT3 signaling pathway and induce polarization of gastric cancer M2-macrophages." (PMID 35479325, 2022). "Activation of Janus kinase 2/signal transducer and activator of transcription (3 JAK2-STAT3) by other cytokines such as Interleukin 6 (IL-6) has also been reported in gastric carcinoma and colon cancer." (PMID 35875085, 2022). "CCL20/CCR6 induced gastric cancer EMT through the activation of the AKT pathway in response to CrkL; similar results were found with CCL21/CCR7 axis activated JAK2/STAT3 signaling pathways in promoting stemness of OSCC EMT progression." (PMID 34943853, 2021).
gastric cancer (continued). "Through analyzing the expression data of 37 gastric cancer cell lines from CCLE, we figured out that ERCC6 mRNA expression was correlated with JAK2 protein expression, and that ERCC8 mRNA expression was related to Src protein expression." (PMID 34316408, 2021). "Tumor-infiltrating lymphocyte (TIL)-driven IFNγ stimulates the JAK2/STAT1 pathway, leading to increased PD-L1 expression in gastric cancer." (PMID 33406733, 2021). "In this study, we worked out that H. pylori infection leads to higher mRNA expression of IL-6, JAK-2 and STAT-3 at the local site of infection which better explains the progression of gastric cancer at the molecular level." (PMID 33569347, 2020). "According to many recent studies, activated JAK2/STAT3 signaling has been observed in several kinds of tumors such as lung, prostate, and gastric cancers." (PMID 31540495, 2019). "Taken together, our results suggest that pantoprazole downregulates JAK2/STAT3 signaling through inducing SHP-1 expression to modulate snail/E-cadherin expression and inhibit cellular migration or invasion in gastric cancer cells." (PMID 30202514, 2018). "We have previously investigated promoter hypermethylation and gene expression of SHP-1 in most of gastric cancer cells and functional effects of SHP-1 on JAK2/STAT3 pathway." (PMID 30202514, 2018). "Taken together, our data suggest that pantoprazole modulate expression of p-JAK2/p-STAT3 (downregulation) and SHP-1 (upregulation) and EMT markers in gastric cancer cells." (PMID 30202514, 2018). "In contrast, adding IL-6 neutralizing antibody or JAK-2 protein tyrosine kinase inhibitor AG490 into the co-culture system significantly reversed CAF-mediated phosphorylation of JAK2 and STAT3 in gastric cancer cells." (PMID 28186964, 2017). "This suggests that B7-H3 silencing suppressed gastric cancer cell migration and invasion by reducing AKT, ERK, and Jak2/Stat3 pathway activation." (PMID 29069741, 2017). "The PD-L1, PD-L2, and JAK2 genes are located on chromosome 9p24.1, and their amplifications have been reported in lymphomas, an EBV-positive type of gastric cancer, and triple-negative breast cancer." (PMID 27050074, 2016). "The PD-L1 and PD-L2 genes localize to 9p24.1 adjacent to JAK2 and there is emerging data that an amplicon targeting this 9p24.1 locus is present in lymphomas and a subset of EBV-positive gastric cancers." (PMID 26317899, 2015). "Ponicidin has significant anti-proliferation effects by inducing apoptosis on gastric carcinoma cells in vitro, and induced apoptosis of MKN28 cells via the pathway regulated by JAK2 and STAT3 signaling pathways." (PMID 25588213, 2015). "Besides, overexpression of JAK2 could promote the migration and invasion of gastric cancer cells." (PMID 25055044, 2014). "In various cancers, including malignant glioma, gastric cancer, salivary adenoid cystic carcinoma, and hepatocellular carcinoma (HCC), B7-H3 promotes epithelial-to-mesenchymal transition (EMT) via the activation of the JAK2/STAT3/Slug signaling pathway." (PMID 40214484, 2025). "Overexpressed C3 could activate JAK2/STAT3 pathway, which has a correlation with the progression of gastric cancer." (PMID 40396123, 2025). "The JAK2/STAT3 pathway is also activated by stem cells in GC through high secretion of IL-6/IL-8, and this contributes to M2-like TAM polarization and, consequently, promotes gastric cancer metastasis." (PMID 38542388, 2024). "The gastric cancer genome is characterized by focal amplification of oncogenes, including receptor tyrosine kinases, such as ERBB2 (HER2), EGFR, ERBB3, VEGF-A, KRAS/NRAS, MET, JAK2, and PD-L1/PD-L2." (PMID 38733489, 2024). "Moreover, CALM2 has been found to stimulate proliferation, migration, invasion, and angiogenesis of HUVECs, as well as M2 polarization of THP1 cells, through the JAK2/STAT3/HIF-1/VEGFA signaling pathway, thereby facilitating gastric cancer metastasis." (PMID 39695099, 2024).